FGF23 (fibroblast growth factor 23)
Diseases named in the same sentence as FGF23 in open-access papers (continued):
Sharing a sentence is not in itself a finding about the gene and the disease.
epidermal nevus syndrome (3 papers, 2016 to 2022). A syndrome characterized by lesions occurring on the face, scalp, or neck which consist of congenital hypoplastic malformations of cutaneous structures and which over time undergo verrucous hyperplasia. "FGF23 secretion may also be observed in association with rare bone diseases such as neurofibromatosis, epidermal nevus syndrome and isolated fibrous dysplasia or in the setting of McCune-Albright." (PMID 27709474, 2016). "Epidermal Nevus Syndrome (ENS), also known as Cutaneous Skeletal Hypophosphatemia Syndrome or Linear Sebaceous Nevus Syndrome, is caused by a mosaic somatic mutation of RAS (Rat Sarcoma genes) which leads to abnormally elevated levels of fibroblast growth factor 23 (FGF23)." (PMID 35899095, 2022). "There are multiple disorders, along with Epidermal Nevus Syndrome (ENS), that result in unusually high circulating levels of FGF23." (PMID 35899095, 2022). "Epidermal Nevus Syndrome (ENS) is a congenital, multisystem disorder that is characterized by multiple cutaneous epidermal nevi that produce abnormally high levels of fibroblast growth factor 23 (FGF23)." (PMID 35899095, 2022).
glomerular diseases (3 papers, 2019 to 2024). "FGF23 increases in glomerular diseases have been associated with corticosteroid use." (PMID 39433982, 2024). "Inconsistent with our findings, previous studies reported higher FGF23 levels in glomerular diseases than in non-glomerular diseases." (PMID 39433982, 2024). "They stated a significantly higher concentration of FGF-23 in patients, in whom the underlying cause of CKD was glomerulopathy." (PMID 31354894, 2019).
gout (3 papers, 2022 to 2025). A condition characterized by painful swelling of the joints, which is caused by deposition of urate crystals. "Finally, we identified a novel association between gout and reduced FGF-23 levels (–30%, approximately –0.35 pg/mL), an observation that warrants further investigation." (PMID 40943671, 2025). "Additionally, gout affected the concentration of FGF-23 by approximately 30%, resulting in a decrease of 0.35 pg/mL." (PMID 40943671, 2025).
hemorrhagic stroke (3 papers, 2020 to 2021). A stroke caused by a bleed on the brain. "Relevant studies have shown that an elevated FGF23 level is a risk factor for ischemia and hemorrhagic stroke in patients with CKD." (PMID 34759797, 2021).
Hypervolemia (3 papers, 2016 to 2021). An increase in the amount of intravascular fluid, particularly in the volume of the circulating blood. "It is noticeable that both hypervolemia and serum level of FGF-23 increase in case of the loss of RUV." (PMID 27871253, 2016). "One study found that elevated FGF23 correlated with hypervolemia in patients on hemodialysis, although another study reported that FGF23, albeit correlating with volume status in patients on hemodialysis, was not reduced by the hemodialysis." (PMID 33000285, 2021).
Hypoalbuminemia (3 papers, 2019 to 2023). The concentration of albumin in the blood circulation is below the lower limit of normal. "Serum FGF23 levels were significantly increased in hypoalbuminemia PTH 150-300 and 300-600 groups than normoalbuminemia patients." (PMID 31839746, 2019). "Hypoalbuminemia significantly increased the fibroblast growth factor-23 (FGF-23) and procollagen type 1N-terminal propeptide (P1NP) in PTH ≤150 pg/mL, PTH 150-300 pg/mL, PTH 300-600 pg/mL groups, whereas no such relation was noted among PTH> 600 ng/dL group." (PMID 31839746, 2019).
hypocalciuric hypercalcemia (3 papers, 2024 to 2025). "It has been suggested that elevated FGF23 levels may distinguish FHH1 from other forms of PTH-dependent hypocalciuric hypercalcemia." (PMID 38386045, 2024).
Kawasaki disease (3 papers, 2013 to 2017). A rare inflammatory disease characterized by an acute febrile, systemic, self-limiting, medium-vessel vasculitis primarily affecting children. "The segregation of the FGF23 polymorphism is significantly related to elevated serum FGF23 levels and cardiac complications in children with Kawasaki disease." (PMID 28977159, 2017). "A SNP in the intron of FGF23 is significantly associated with higher serum FGF23 levels and cardiac abnormalities in children with Kawasaki disease." (PMID 26483756, 2015). "Fibroblast Growth Factor (FGF) 23 influences endothelial integrity and few reports have studied the association between FGF23 and Kawasaki syndrome (KS), a childhood vasculitis displaying a high risk of subsequent cardiac abnormalities (CaA)." (PMID 24168888, 2013).
kidney inflammation (3 papers, 2017 to 2024). "Serum FGF23 levels begin to rise in NS patients before CKD G1, indicating that increased FGF23 levels are linked to both the progression of nephritis and early detection of abnormal mineral metabolism in patients with NS." (PMID 39200324, 2024). "In CKD, kidney inflammation downregulates Klotho, resulting in FGF-23 resistance and the need or even higher FGF-23 levels." (PMID 28498348, 2017).
liver cirrhosis (3 papers, 2021 to 2026). "There has been only one report that revealed that alcoholics, particularly those with liver cirrhosis, showed elevated C-terminal FGF23, although intact FGF23 was not measured in that study." (PMID 34901334, 2021).
liver dysfunction (3 papers, 2013 to 2025). "A recent study demonstrated that hepatic FGF23 synthesis was induced in a murine model of chronic alcoholism with liver dysfunction." (PMID 39963340, 2025). "Alcoholics, particularly those with liver dysfunction, show higher C-terminal FGF23 levels." (PMID 34901334, 2021). "The re-expression of FGF23 in the liver is independent of the presence of a virus or a hepatocarcinoma but seems to reflect the severity of liver dysfunction." (PMID 23825530, 2013).
lung diseases (3 papers, 2017 to 2023). "In order to assess our in vitro data for relevance in vivo, we measured soluble KL and FGF23 levels in plasma samples from 8 control patients without lung disease and 48 CF individuals." (PMID 29085059, 2017). "Since FGF23 and KL were not detectable in BAL fluid, we investigated possible sources of plasma FGF23 elevation in CF lung disease." (PMID 29085059, 2017).
mineral metabolism disorders (3 papers, 2012 to 2025). "Additional preclinical and clinical studies are warranted to determine whether blocking FGF23 with burosumab will provide a new targeted intervention for mineral metabolism disorders in CKD." (PMID 36209090, 2022).
myelodysplastic syndrome (3 papers, 2020 to 2024). A clonal hematopoietic disorder characterized by dysplasia and ineffective hematopoiesis in one or more of the hematopoietic cell lines. "Patients with myelodysplastic syndrome (MDS) characterized by impaired hematopoiesis in the bone marrow have a higher FGF23 plasma concentration that is associated with anemia and lower bone mineralization." (PMID 33520985, 2020). "Indeed, we recently showed that increased FGF-23 levels are associated with ineffective erythropoiesis and impaired bone mineralization in myelodysplastic syndromes (MDS)." (PMID 33143240, 2020).
myocardial ischemia (3 papers, 2014 to 2023). A disorder of cardiac function caused by insufficient blood flow to the muscle tissue of the heart. "A recent study confirmed that FGF23 can bind FGFR4 in cardiomyocytes to enhance hypertrophy, interestingly, our data in this study showing that FGFR4 is also expressed in cardiac fibroblasts and upregulated in response to myocardial ischemia." (PMID 27579618, 2016). "Thus, the profound rise in FGF-23 appears to be due to the neuroendocrinologic and/or hemodynamic impacts of CS rather than to the acute myocardial ischemia per se." (PMID 25528363, 2014). "It is unclear why FGF23 did not exert profibrotic effect in sham mice, the upregulated FGFR4 in response to myocardial ischemia may be attributable." (PMID 27579618, 2016).
neurofibromatosis type 1 (3 papers, 2020 to 2025). A clinically heterogeneous, neurocutaneous genetic disorder characterized by cafe-au-lait spots, iris Lisch nodules, axillary and inguinal freckling, and multiple neurofibromas. "We here describe a first rare case of a 65-year-old woman with neurofibromatosis type 1 associated with hypophosphatemic osteomalacia in which a high serum fibroblast growth factor 23 level was confirmed." (PMID 32384911, 2020).
osteogenesis imperfecta (3 papers, 2022 to 2025). Osteogenesis imperfecta (OI) comprises a heterogeneous group of genetic disorders characterized by increased bone fragility, low bone mass, and susceptibility to bone fractures with variable severity. "One study evaluated the effect of intravenous pamidronate administration on serum FGF23 levels in patients with osteogenesis imperfecta treated with two cycles of 3-day pamidronate infusion." (PMID 40649786, 2025). "The aim of this study was to evaluate FGF23 levels among children with osteogenesis imperfecta and their differences from reference values in a healthy population of children and adolescents." (PMID 40649786, 2025). "The level of FGF23 in patients with osteogenesis imperfecta is lower among older children and those having a higher BMI." (PMID 40649786, 2025). "The purpose of this study was to evaluate the concentration of FGF23 among children with osteogenesis imperfecta and the differences in reference values in a healthy population of children and adolescents." (PMID 40649786, 2025). "Then, this study sought to evaluate how the course of osteogenesis imperfecta, including type of disease, number of bone fractures, and bone mineral density, are related to FGF23 concentration." (PMID 40649786, 2025). "The study analyzed the results of FGF23 levels in a group of children and adolescents with osteogenesis imperfecta." (PMID 40649786, 2025). "A clinical study previously demonstrated that the intravenous administration of pamidronate to patients with osteogenesis imperfecta rapidly decreased serum intact FGF23 levels, which suggested that bone turnover influences serum FGF23 levels." (PMID 35909535, 2022). "FGF23 levels were not related to the number of fractures (p = 0.749), the number of sodium pamidronate cycles administered (p = 0.580), bone mineral density parameters (Z-score), the form of osteogenesis imperfecta (p = 0.156), or the genetic test result (p = 0.573)." (PMID 40649786, 2025).
otitis media (3 papers, 2014 to 2023). Inflammation of the anatomical structures of the middle ear, which is most often caused by an infectious process. "Given the potential temporal and mechanistic overlap of initiation of FGF23 activity and Eustachian tube development, this work suggests a possible role for FGF23 in the genetic predisposition to otitis media, a link that warrants further investigation." (PMID 25243481, 2014). "Animal models suggest that FGF23 is essential for normal development of the middle ear and functioning of the middle and inner ear, and that FGF23 deficiency may predispose to otitis media." (PMID 37547321, 2023). "We also demonstrate a connection between FGF23 deficiency and predilection to otitis media." (PMID 25243481, 2014). "Given the extensive middle ear malformations and the overlap of initiation of FGF23 activity and Eustachian tube development, this work suggests a possible role for FGF23 in otitis media." (PMID 25243481, 2014). "Our findings also suggest a potential role for FGF23 in otitis media, a clinically important disease that afflicts 75–90% of Americans at least once before 3 years of age." (PMID 25243481, 2014). "ENPP1 deficiency is known to cause elevated serum levels of FGF23 in Enpp1 mutant mice, and excess FGF23 secreted in the middle ear may trigger mucoperiosteum proliferation, which may contribute to the development of otitis media." (PMID 27959908, 2016).
parathyroid hyperplasia (3 papers, 2014 to 2021). A hyperplasia that involves the parathyroid gland. "High FGF23 levels reduce the renal production of 1,25D3, which in turn promotes parathyroid hyperplasia." (PMID 32913635, 2020). "In animals with normal renal function, the elevation in FGF23 causes a reduction in PTH production, but as parathyroid hyperplasia develops, there is a lower expression of parathyroid FGFR and Klotho receptors, which prevent any inhibitory effect of FGF2310." (PMID 32913635, 2020). "Besides phosphate retention, FGF-23 contributes to progression of parathyroid hyperplasia." (PMID 25295189, 2014). "However, with the development of parathyroid hyperplasia, Klotho expression is reduced and the high FGF23 is not able to inhibit PTH production and parathyroid cell proliferation." (PMID 32913635, 2020).
rhabdomyolysis (3 papers, 2011 to 2026). Necrosis or disintegration of skeletal muscle often followed by myoglobinuria. "Several studies included patients with AKI due to causes other than rhabdomyolysis, but these were published 30 or more years ago and did not measure more novel regulators of mineral metabolism, such as fibroblast growth factor-23 (FGF-23)." (PMID 21906363, 2011). "In this cross-sectional case series, we report for the first time that critically ill patients with AKI due to causes other than rhabdomyolysis have elevated FGF-23 levels compared with critically ill controls." (PMID 21906363, 2011). "We sought to determine the impact of AKI on FGF-23 and parathyroid hormone (PTH) levels in patients with AKI due to causes other than rhabdomyolysis." (PMID 21906363, 2011). "To date, only one case report has explored the impact of AKI on levels of FGF-23 and that was in the setting of rhabdomyolysis." (PMID 21906363, 2011). "Nevertheless, this is the first study to report an association between FGF-23 and non-rhabdomyolysis-related AKI, and that among patients with AKI, higher FGF-23 levels are associated with an increased risk of death." (PMID 21906363, 2011).
seminoma (3 papers, 2023 to 2025). A radiosensitive malignant germ cell tumor found in the testis (especially undescended), and extragonadal sites (anterior mediastinum and pineal gland). "This suggests that the expression of FGF23 is linked with the transformation of GCNIS to the invasive EC and is not a result of duplication of chromosome 12p which is also prevalent in classical seminoma." (PMID 40279260, 2025). "FGF6 (STM: > 70%; GCT: 5%) and FGF23 (STM: > 70%; GCT: 5%) were amplified in the same eight GCT samples (mainly non-seminomas)." (PMID 37726478, 2023). "IHC confirmed the marked expression of FGF23 solely in OCT4-positive GCNIS cells that also expressed FGFR1, while Klotho was exclusively expressed in normal germ cells and not found in any of the OCT4-positive cancer cells including seminoma and EC." (PMID 40279260, 2025). "Using TCGA mRNA expression of anabolic (CYP2R1, CYP27A1 and CYP27B1) and catabolic (CYP24A1) Vitamin D enzymes, positive (PTHLH, IFNG, and TNF) and negative (FGF23) feedback regulators could also clearly distinguish between pure seminomas and NSGCT." (PMID 37242266, 2023). "The systemic master regulator of phosphate, FGF23, is highly expressed in GCNIS, EC, and hESC but not in classical seminoma." (PMID 40279260, 2025). "Thus, expression of FGF23 was investigated in human testicular specimens containing ‘normal testis’ (adjacent tissue to TGCT/GCNIS without presence of malignant cells), Sertoli-cell-only pattern, GCNIS, seminoma, and EC with or without teratoma components." (PMID 40279260, 2025).
viral infections (3 papers, 2016 to 2023). "Currently, most studies evaluating the association between plasma FGF23 levels and infectious morbidity were performed before the SARS-CoV-2 pandemic and evaluated other infection-related hospitalizations caused by severe bacterial and viral infections." (PMID 36828412, 2023). "The majority of our experience exploring the association between plasma FGF23 levels, morbidity, and mortality from infectious causes comes from studies performed long before the SARS-CoV-2 pandemic and included infection-related hospitalizations caused by both bacterial and viral infections." (PMID 37637614, 2023). "Alternatively, FGF23 may be marker of an inflammatory response to these viral infections." (PMID 27176000, 2016). "However, among HIV-positive individuals, we found significant associations of HCV co-infection and unsuppressed HIV RNA levels with higher FGF23 levels that require further exploration of the interaction between viral infection and/or immune activation and bone disease." (PMID 27176000, 2016).
acromegaly (2 papers, 2014 to 2021). Acromegaly is an acquired disorder related to excessive production of growth hormone (GH) and characterized by progressive somatic disfigurement (mainly involving the face and extremities) and systemic manifestations. "Recent data suggest that the increase in serum phosphate under GH treatment or acromegaly is unexpectedly associated with upregulation of the phosphaturic FGF23/Klotho axis, suggesting counter-regulatory mechanisms or an FGF23 resistance induced by GH-stimulated Klotho secretion in the kidney." (PMID 34199514, 2021). "Consistently, increased FGF23 levels were also noted in some acromegaly patients." (PMID 25198618, 2014).
acute alcoholic hepatitis (2 papers, 2024). "FGF23 expression was compared in livers from alcoholic hepatitis patients and healthy controls." (PMID 38479224, 2024). "Interestingly, in our current study, we showed that FGF23 is mainly expressed in hepatocytes and its expression is induced in livers of alcoholic hepatitis and alcoholic cirrhosis patients." (PMID 38479224, 2024). "To test this hypothesis, first we examined the expression level of FGF23 in publicly available Gene Expression Omnibus (GEO) datasets of alcoholic hepatitis (GSE143318) and alcoholic cirrhosis (GSE167308) patients." (PMID 38479224, 2024). "Moreover, we validated the ERRγ gene expression in the GEO datasets of alcoholic hepatitis (GSE143318) and alcoholic cirrhosis (GSE167308) patients, which we used to check FGF23 expression." (PMID 38479224, 2024).
adenoma (2 papers, 2011 to 2025). A neoplasm arising from the epithelium. "In the FGF23-producing adenoma sample (FGF_7), a fusion transcript involving exon 20 of FN1 and exon 11 of RET genes was detected." (PMID 41373459, 2025). "The P for trend for the relationship between increasing FGF-23 concentration and odds for adenoma was statistically significant (P=.03)." (PMID 21383962, 2011). "We propose that the observed suppression of 1,25(OH)2D by FGF-23 results in an increased odds for metachronous adenoma in individuals with higher FGF-23 concentrations compared to those with lower levels." (PMID 21383962, 2011).